CUX1 (cut like homeobox 1)
Diseases named in the same sentence as CUX1 in open-access papers (continued):
Sharing a sentence is not in itself a finding about the gene and the disease.
tumor (continued). "Given the dual roles of CUX1 as both an oncogene and a tumor suppressor depending on the context, CUX1 molecular roles have been extensively studied to explore its potential associations with DNA repair processes." (PMID 37744879, 2023). "Our data indicate that in hematopoietic cells, the tumor suppressive role of CUX1 is attributable to the full-length protein." (PMID 34997000, 2022). "We have previously established that CUX1 functions as a tumor suppressor in hematopoietic cells across multiple organisms." (PMID 34997000, 2022). "The Cancer Genome Atlas (TCGA) characterization of 276 human colorectal cancers ranked CUX1 as the fifth gene on a scale showing a correlation between tumor aggressiveness and a combined score based on gene expression and somatic copy number alterations." (PMID 36176767, 2022). "CUX1 is a tumor suppressor that stabilizes the PI3K signaling pathway and decreases the number of normal cells transforming into tumor cells." (PMID 36408177, 2022). "The CUT-like homeobox 1 (CUX1) is described as a tumor-suppressor gene that is thought to act on DNA damage repair in response to oxidative stress." (PMID 35456443, 2022). "Such a long latency period indicates that CUX1 is probably not an oncogene per se, and that, certainly, other cooperating events are required for tumour development in cells that overexpress CUX1." (PMID 36176767, 2022). "The cooperation of CUX1 with a RAS oncogene in tumour development was confirmed by performing lentiviral infections in the lung of mice." (PMID 36176767, 2022). "Consistent with a tumor suppressor role, CUX1 knockdown in mouse models leads to MDS/MPN that is reminiscent of human disease." (PMID 34997000, 2022). "In our p110 CUX1 mouse model, tumor progression was much more accelerated compared to mice expressing full-length CUX1." (PMID 34070180, 2021). "In our previous study, we have demonstrated oncogenic roles of CUX1 and its generated circRNA in aerobic glycolysis and tumor progression." (PMID 34579723, 2021). "In our previous study, we also found that the CUX1 level was associated with tumor WHO grade and the malignant proliferation index in glioma, which provides additional evidence for the investigation of the CUX1-drived molecular mechanism in gliomagenesis." (PMID 34422906, 2021). "In the conditional p110 CUX1 mouse model, tumor development was much more accelerated compared to the model with ubiquitous expression of p200 CUX1." (PMID 34070180, 2021). "CircCUX1: The CUX1 gene gives rise to the 393-nucleotide long nuclear circCUX1 (hsa_circ_0132813) that promotes cell proliferation, aerobic glycolysis, and tumor aggressiveness in neuroblastoma tumor cells." (PMID 34449657, 2021). "As a homeodomain transcription factor, CUX1 regulates cell cycle progression, proliferation, migration, and invasiveness of numerous tumor cell lines." (PMID 34579723, 2021). "In different cancer types, CUX1 has been described either as a tumor suppressor or an oncogenic driver." (PMID 34070180, 2021). "CUX1, identified in the sensitive network, is a tumor suppressor and it’s lose promotes tumorigenesis." (PMID 34879849, 2021). "While the expression of the respective proteins and the CUX1-induced tumor-promoting effects (tumor cell proliferation and invasion) were significantly reversed by silencing Axin2 or β-Catenin expression (p < 0.05)." (PMID 34422906, 2021). "p110 CUX1 is generated by proteolytical processing of p200 CUX1 via the endopeptidase cathepsin L in several tumor models." (PMID 34070180, 2021). "Taken together, both genetic in vivo models suggest that CUX1 acts as an important accelerator of tumor development, with p110 CUX1 as cleavage product of oncogenic cathepsin L activity being the most active CUX1 variant." (PMID 34070180, 2021). "Our group has shown that CUX1 modulates tumour progression in pancreatic adenocarcinoma by mediating tumour cell proliferation, migration and angiogenesis." (PMID 32707646, 2020).
tumor (continued). "Several studies have proposed an important role for CUX1 in tumorigenesis and tumour progression in solid cancer." (PMID 32707646, 2020). "CUX1 has been characterised as a haploinsufficient tumour suppressor gene, however, it is also overexpressed in many advanced cancers." (PMID 32707646, 2020). "Previously, we already described a gradual increase in CUX1 RNA expression during tumour progression in the RIP1Tag2 model." (PMID 32707646, 2020). "Functional in vitro data highly support this association by identifying effectors of the apoptosis machinery, such as caspases-3 and -9 as mediators of CUX1-induced resistance to apoptosis and tumour progression." (PMID 32707646, 2020). "Both sides of evidence, respectively, support the tumor suppressive or oncogenic roles of CUX1 in tumor development and progression." (PMID 32547943, 2020). "Functionally, CUX1 upregulated expression of caspases and death associated protein kinase 1 (DAPK1), known as mediators of tumour progression and resistance to cytotoxic drugs." (PMID 32707646, 2020). "Several previous studies in other cancer types have identified a role for CUX1 in mediating tumour progression via its role in cell migration and invasiveness." (PMID 32180898, 2020). "One possible explanation comes from the protective role of CUX1 in DNA damage repair, because the machinery of DNA damage repair is a double-edge sword in tumor initiation and progression." (PMID 32547943, 2020). "Although some previous studies have indicated the oncogenic role of CUX1 in tumor progression, other studies also exhibit substantial evidence to support CUX1 as an important tumor suppressor in many types of cancers." (PMID 32547943, 2020). "The third explanation derives from the presence of CUX1 in both tumor cells and TAMs and the inhibitory effects of CUX1 on the NF-κB signaling." (PMID 32547943, 2020). "So far, the short isoforms of CUX1, such as p110 and p75 CUX1, seem to carry oncogenic features, while the exact role of full-length CUX1 in tumor progression remains elusive." (PMID 32547943, 2020). "Circ‐CUX1 enhanced the expression of CUX1 at transcriptional level, and tumor‐promoting functions of circ‐CUX1 were mediated, at least in part, through interacting with EWSR1 protein in NB cells." (PMID 31709724, 2019). "In this study, we identify CUT‐like homeobox 1 (CUX1) as a transcription factor facilitating aerobic glycolysis and tumor progression in NB." (PMID 31709724, 2019). "In this study, circ‐CUX1 was identified as an intron‐containing circRNA up‐regulated in tumor tissues and cells." (PMID 31709724, 2019). "Together, these results revealed that CUX1/FGF1/HGF signalling is the main target of DPPA in the inhibition of tumour angiogenesis." (PMID 30010249, 2018). "Ectopic expression of p200 CUX1 increased clonogenic efficiency following irradiation in the three tested tumor cell lines." (PMID 28147323, 2017). "To investigate the requirement for CUX1 in the resistance to radiation, we established populations of tumor cell lines stably carrying a lentiviral vector expressing a CUX1 shRNA under the control of a doxycycline-inducible promoter." (PMID 28147323, 2017). "The interpretation of these results is complicated by the fact that in many tumor cell lines, CUX1 expression levels impacts on clonogenic efficiency even in the absence of radiation." (PMID 28147323, 2017). "The Cut homeobox 1 (CUX1) gene has been characterized as a haploinsufficient tumor suppressor gene, but is also overexpressed in many advanced cancers." (PMID 28147323, 2017). "Consistent with the high levels of p110 CUX1, we found that CathepsinL was strongly overexpressed in Ptenpc−/− tumours." (PMID 27941799, 2016). "Surprisingly, WB analysis revealed that p110 CUX1 was overexpressed in Ptenpc−/− tumours, while p200 CUX1 was mainly expressed in Ptenpc+/+ prostates." (PMID 27941799, 2016).
tumor (continued). "The biochemical and cellular functions of CUX1 involved in tumor suppression and/or progression remain to be fully characterized." (PMID 25682875, 2015). "In a recent study, the authors claimed that 9 out of 10 unlisted cell cycle genes were inversely correlated with CUX1 expression, thereby implying that its tumor-suppressing function involved the repression of cell cycle genes." (PMID 24618719, 2014). "CUX1 knockdown in six human tumor cell lines that display autocrine activation of the Wnt/β-catenin pathway showed that CUX1 is required for maximal expression of WNT genes." (PMID 25217618, 2014). "We noted that the expression of several CUX1 isoforms was elevated in cell lines as compared to the corresponding tumor samples." (PMID 24618719, 2014). "We conclude that CUX1 is required for maximal expression of WNT genes in human tumor cell lines that display autocrine activation of the Wnt/β-catenin pathway." (PMID 25217618, 2014). "Using lentiviral infections in the lung, we confirmed that p200 CUX1 cooperates with activated Kras in tumor formation." (PMID 24618719, 2014). "We reasoned that such an unbiased approach would better recapitulate the process of tumor development as it occurs in humans and therefore reveal significant genetic and epigenetic changes that cooperate with CUX1 overexpression in tumor development." (PMID 24618719, 2014). "The vertebrate homologue of Cut, Cux1, has a well-documented function in cell differentiation during normal development as well as in tumor initiation and progression in specific cancer types." (PMID 22438831, 2012). "And fourth, induced down-regulation of Cux1 in subcutaneous xenograft tumors leads to activation of apoptosis and to reduced tumor growth." (PMID 22438831, 2012). "However, in contradiction, additional evidence supports a model of haploinsufficiency, where reduced CUX1 expression contributes to tumor development (CUX1 as a tumor suppressor gene)." (PMID 37744879, 2023). "Therefore, the evidence indicates that increased CUX1 can promote tumor progression (CUX1 as an oncogene)." (PMID 37744879, 2023). "Interestingly, an increase on CUX1 expression was found to cooperate with RAS in promoting tumor formation in mice." (PMID 37744879, 2023). "Even in Drosophila models, the CUX1 orthologue, cut, exerts tumor suppressive activity." (PMID 34997000, 2022). "Moreover, miR-16-5p tumor suppressor impact has been partially decreased by transfection of circ-CUX1 overexpressing vectors." (PMID 36348403, 2022). "The net effect of CUX1 overexpression may be the disruption of endogenous CUX1 tumor suppressor activity." (PMID 34997000, 2022). "Circ-CUX1 binds to EWSR1 and promotes interaction with MAZ, leading to transactivation of MAZ and transcriptional alterations of CUX1 and other genes associated with tumor progression." (PMID 35116058, 2021). "However, the much more aggressive phenotype seen in p110 CUX1 mice supported the notion that this CUX1 cleavage product had a strong tumor-promoting impact." (PMID 34070180, 2021). "For example, CUX1 encodes for a transcription factor that has been demonstrated to bind to the Snail promoter, which ultimately leads to increased epithelial-to-mesenchymal transition (EMT), tumor migration, and invasion." (PMID 34439480, 2021). "The expression of these proteins and the CUX1-induced tumor-promoting effect could be reversed by silencing Axin2 or β-catenin expression." (PMID 34422906, 2021). "CUX1 expression was almost undetectable in 21 primary tumours (20.2%) and 10 metastases (27.0%)." (PMID 32707646, 2020).
tumor (continued). "While loss of heterozygosity and/or mutations of CUX1 have been frequently detected in many types of cancers, genomic amplification, and overexpression of CUX1 have also been reported in cancer tissues and are correlated with higher tumor grade and poor prognosis." (PMID 32547943, 2020). "It seems paradoxical that CUX1 possesses both oncogenic and tumor-suppressive features." (PMID 32547943, 2020). "Notably, recent researches have corroborated that the activation or overexpression of CUX1 in tumor progression is a crucial contributor to the growth, invasion, and metastasis of tumor cells." (PMID 33344221, 2020). "Circ-CUX1 can directly interact with EWSR1 and facilitate EWSR1-MAZ interaction, resulting in transactivation of MAZ and transcriptional alteration of CUX1 and other genes associated with tumor progression." (PMID 32547943, 2020). "Interestingly, CUX1 has been recently recognized as a haploinsufficient tumor suppressor, which is paradoxically overexpressed in tumor cells." (PMID 32547943, 2020). "We hypothesise that a different stage and tumour biology, as well as sample origin between treatment-naïve and pretreated patients also impact on both CUX1 and caspases protein levels." (PMID 32707646, 2020). "But whether CUX1 functions as an oncogene or tumor suppressor is still under debate, because the results of CUX1 studies on tumor development are controversial." (PMID 32547943, 2020). "Therefore, further studies specifically targeting full-length CUX1 or short isoforms are required to decipher the role of CUX1 in tumor progression." (PMID 32547943, 2020). "Therefore, deciphering the roles of different CUX1 isoforms and in different tumor stages is required to establish a CUX1-based therapeutic strategy for cancer treatment." (PMID 32547943, 2020). "We further observed the potential effects of circ‐CUX1 on biological features of tumor cells." (PMID 31709724, 2019). "The 393‐nt circ‐CUX1, consisting of exon 2 and partial intron 2 of CUX1, was detected by RT–PCR with divergent primers and Sanger sequencing, and its expression levels were significantly elevated in many tumor cell lines." (PMID 31709724, 2019). "Upon irradiation, CUX1 knockdown reduced clonogenic efficiency in all tested tumor cell lines." (PMID 28147323, 2017). "We then checked the expression levels of CUX1 in Ptenpc−/− tumours." (PMID 27941799, 2016). "Indeed, a higher tumor multiplicity, higher grade benign tumors, greater benign tumor burden, and the only adenocarcinoma was observed when CUX1 was co-expressed KRASG12V." (PMID 24618719, 2014). "In summary, although a small number of mice were assessed, the calculated summed area of all tumors indicated that the total tumor burden was 7.5-fold higher in mice infected with a lentivirus expressing both CUX1 and KRASG12V than in mice that received KRASG12V alone (p<0.05, Mann-Whitney test)." (PMID 24618719, 2014). "On the other hand, the role of CUX1 in base excision repair may explain how haplodeficient expression of CUX1 may contribute to tumor initiation." (PMID 24618719, 2014). "In particular, the comprehensive molecular characterization of human colon and rectal cancer rated CUX1 as the fifth most highly relevant gene (p value = 3×10−10) on a scale showing the correlation between tumor aggressiveness and gene expression/somatic copy number alterations." (PMID 24618719, 2014). "First, tumor samples are obviously heterogeneous and may include cells that express lower CUX1 levels." (PMID 24618719, 2014). "Aberrant expression of CUX1 could be related to tumour progression in a number of cancers, but to date studies of SMZL have not demonstrated any relationship between CUX1 and this NHL." (PMID 21957467, 2011).
tumor (continued). "Previous studies using a Drosophila cancer model and a CUX1 insertion mutation mediated by a mouse transposon found that when CUX1 is deleted, it will abnormally activate the PI3K signaling pathway, thus promoting tumor growth and sensitivity to PI3K/AKT inhibitors." (PMID 36408177, 2022). "In an initial approach to determine whether tumor suppressor loss could induce adaptive cellular responses vital for survival, we performed genome-wide CRISPR/Cas9 drop-out screens in isogenic myeloid cancer cells that differed solely in CUX1 status." (PMID 33931647, 2021). "However, the exact role of p200 CUX1 in tumor progression is still under debate." (PMID 32547943, 2020). "Therefore, more precise and sophisticated studies, for example, by employing CRISPR/Cas9 genome editing approach to establish either p200 CUX1 unprocessable or p200 CUX1 null mutants, are required to define the roles of p200 CUX1 and its isoforms in tumor development." (PMID 32547943, 2020). "Tumor cell survival following ionizing radiation was shown to decrease following CUX1 knockdown but to increase following ectopic expression of the full-length p200 CUX1 protein, while results from laser micro-irradiation indicate that CUX1 proteins are recruited to DNA damage." (PMID 28147323, 2017). "Many studies concur to suggest that CUX1 may function as a haploinsufficient tumor suppressor." (PMID 24618719, 2014). "The chromosomal position and function of CUX1 suggest that it may act as a tumour-suppressor gene." (PMID 21957467, 2011). "In contrast, CUX1 and ANGPT2 were upregulated in metastatic fibroblasts, and SP3 was upregulated in metastatic tumor cells relative to their expression in the primary tumor." (PMID 40095604, 2025). "Kühnemuth and Michl demonstrated that the Cut-like homeobox 1 (CUX1), a homeodomain transcription factor expressed in different tumor types, acts as an antagonist of NF-κB signaling in TAMs." (PMID 38397187, 2024). "In pancreatic (PDA) cancer, the transcription factor Cut like homeobox 1 (CUX1) is an important modulator of TAM phenotype plasticity and functions and it is highly expressed not only in PDA tumor cells but also in PDA TAMs." (PMID 38397187, 2024). "Among these genes, CDKN2A, CDKN2B, CUX1, LRP1B and PTPRD were retrieved as tumor suppressors from the TSGene database." (PMID 38831459, 2024). "While there is no recurrent gene amplification that was observed, the following genes were amplified in two tumor samples: MET, SMO, ERBB2, BRAF, EZH2, SRSF2, CUX1, and CEBPA." (PMID 38164123, 2024). "Our previous findings indicate that CUX1 is highly expressed in PDAC and mediates tumor cell proliferation, invasiveness and resistance to apoptosis." (PMID 34070180, 2021). "Since CUX1 has been identified as transcriptional repressor and its activity induced tumour cell survival and migration, accompanied by tumour progression and shortened survival in several tumour entities, DAPK1 may be an integral part of the oncogenic CUX1-mediated orchestra." (PMID 32707646, 2020). "CUX1 (CUT-like homeobox) is shown to be related to both progression and suppression of tumor, but a haploinsufficient tumor suppressor gene and its overexpression are seen in advanced cancers." (PMID 32992741, 2020). "Therefore, if CUX1 can inhibit NF-κB signaling in both tumor cells and TAMs, CUX1-mediated inhibition on NF-κB signaling in tumor cells or TAMs may, respectively, suppress or promote tumor development, which may contribute to the paradoxical roles of CUX1 to tumor development." (PMID 32547943, 2020). "Therefore, although CUX1 can increase Snailexpression which subsequently binds ER-α promoter to suppress it, we show that there is also direct bindingof ER-α promoter by CUX1, which alludes to the multiple cooperative paths thatcancer cells take to ensure silencing of tumor suppressors." (PMID 30964885, 2019).